CRP (C-reactive protein)
Diseases named in the same sentence as CRP in open-access papers (continued):
Sharing a sentence is not in itself a finding about the gene and the disease.
asthma (continued). "Interestingly, there was a trend (not significant) for patients in the low CRP group to demonstrate more asthma symptoms compared to the high CRP group." (PMID 28066689, 2016). "In patients with asthma the potential of serum CRP, SAA and fibrinogen in recognizing local or systemic inflammation has been shown specially serum CRP which is a known parameter of inflammatory process, is sensitive to changes and readily accessible with low cost." (PMID 26958331, 2016). "On the other hand, increasing serum CRP is a consequence of inflammatory process in asthma." (PMID 26958331, 2016). "Supporting the concept of low grade systemic inflammation in asthma, we found a mild but significant increase in fibrinogen levels in eosinophilic and neutrophilic asthma, while increase in CRP was essentially observed in asthmatics with intense airway neutrophilic infiltration, as previously shown." (PMID 27044366, 2016). "In addition, markers of systemic inflammation (IL-6, CRP, alfa-dimer, and fibrinogen) were the highest in patients with permanent asthma even though patients were using modern controller asthma medication." (PMID 27212806, 2016). "In this study where CRP testing and pulse oximetry were carried out as routine, chest findings, together with the results of CRP and oxygen saturation were stronger predictors in choosing the type of treatment in patients suffering from exacerbation of asthma or COPD than were respiratory symptoms." (PMID 25887285, 2015). "Since our results indicated that sCD14 serum levels are particularly increased in bacterial pneumonia, we analyzed the usefulness of sCD14 serum levels to differentiate bacterial pneumonia from CF, asthma and healthy controls in comparison to the traditionally used markers CRP and WBC." (PMID 20302606, 2010). "Thus, in addition to asthma medications, the use of CPAP therapy controls both airway and systemic inflammation and may enhance asthma control by decreasing FeNO and CRP." (PMID 40662069, 2025). "In this study, the use of the ANN genetic algorithm method could accurately predict the levels of effects of saffron supplementation on anti-inflammatory factors [anti-heat shock protein (Hsp) and C-reactive protein (CRP)] in asthma with an accuracy of 96.5% and 98.9%." (PMID 38023986, 2023). "Additionally, it has also been revealed that elevated serum biomarkers have been associated with asthma; however, CRP failed to reveal a statistically significant association." (PMID 38021559, 2023). "Furthermore, we found that neither C-reactive protein nor asthma increased the risk and severity of myopia." (PMID 36229775, 2022). "Neither C-reactive protein nor asthma was associated with an increased risk and severity of myopia, indicating local proinflammation factors rather than systematic factors could promote myopia onset and progression." (PMID 36229775, 2022). "Neither C-reactive protein nor asthma increased the risk and severity of myopia." (PMID 36229775, 2022). "Furthermore, we exhibited that neither C-reactive protein nor asthma increased the risk and severity of myopia." (PMID 36229775, 2022). "Furthermore, they investigated whether this prothrombotic state is due to chronic inflammation, and showed that asthma was characterized by 62% higher plasma Il-6 and 35% higher TNFα, along with higher CRP, fibrinogen, as well as α2-macroglobulin and PF-4." (PMID 33608061, 2021). "Indeed, elevated serum CRP levels have been correlated with decreased pulmonary function and increased sputum eosinophilic cationic protein levels and eosinophil numbers in steroid naïve asthma patients." (PMID 32246830, 2020). "Interestingly, CRP OR = 1.05 [95% CI (0.92, 1.19)] showed no clear association with adult-onset asthma." (PMID 31217483, 2019). "Thus, CRP theoretically may serve as a valuable tool for identifying systemic inflammation in asthma." (PMID 30974772, 2019).
asthma (continued). "Furthermore, in this group, airway responsiveness, asthma control, and asthma-related quality of life all associated with signs of non-type 2 inflammation, such as blood neutrophil count, CRP, HNL, IL-8, and MMP-1." (PMID 30834110, 2019). "Interestingly, the association between CRP and IQ was found to be non-significant after adjusting for confounders only in the atopic group, suggesting the association is only present when asthma and/or eczema are not present." (PMID 29198208, 2018). "Based on this finding, we hypothesized that a hypercoagulable state in asthma is related to the systemic inflammatory response largely mediated by interleukin (IL)-6, which is the most important inducer of the synthesis of acute phase proteins, including CRP." (PMID 28429138, 2017). "Moreover, some authors have also demonstrated that CRP dosage may be very useful in distinguishing CAP from exacerbations of asthma or COPD, with optimal sensitivity and specificity (respectively 0.91 and 0.93) at a cut-off value of 48 mg/L." (PMID 26772604, 2016). "Furthermore, damaged lung tissue itself may be a source of sustained signal for synthesis of CRP suggesting a possible contributive role for CRP in perpetuation of asthma." (PMID 26958331, 2016). "In asthma, uncontrolled cases (ACT score <15) showed CRP elevations >3 mg/L (OR: 2.1; 95% CI: 1.4–3.2), suggesting systemic inflammation is driven more by OSA than asthma alone." (PMID 40662069, 2025). "The systemic inflammation present in patients with asthma was reflected by CRP levels, which also increased with severity (except in the GINA V group), and antitrypsin levels seemed to follow the CRP pattern." (PMID 40508213, 2025). "Elevated levels of inflammatory biomarkers, such as C-reactive protein (CRP) and IL-6, are reported in patients with severe asthma." (PMID 40823190, 2025). "Individuals with the CC genotype exhibited significantly more severe asthma, along with elevated levels of BEC, ECP, hs-CRP, and total IgE." (PMID 39871194, 2025). "Elevated levels of proinflammatory mediators such as substance P, interleukin-6 (IL-6), and C-reactive protein (CRP) have been observed in both conditions, biologically supporting the coexistence of asthma and fibromyalgia." (PMID 41017472, 2025). "The present study aimed to investigate the effects of metformin on BS control, CRP levels (as an inflammatory marker), ACT score, PFT including FEV1, FVC, and FEV1 to FVC ratio, and clinical outcomes in patients with concurrent asthma and MetS." (PMID 40787554, 2025). "For instance, individuals at risk for BD with higher baseline levels of interleukin (IL)-6, tumour necrosis factor (TNF)-α, and C-reactive protein (CRP) and adolescents with asthma were more prone to developing BD." (PMID 38388844, 2024). "In this exploratory study, we had available measures for two inflammatory biomarkers in the Vitamin D Antenatal Asthma Reduction Trail (VDAART) mother child-cohort; interleukin-8 (IL-8) and CRP, during early and late pregnancy in a mother–child cohort." (PMID 36499584, 2022). "In obese subjects with asthma, the metabolically active adipose tissue releases proinflammatory mediators, including IL-6, TNF-α and C-reactive protein (CRP), and adipokines such as leptin, which are central to the innate immune pathways." (PMID 35565792, 2022). "In other cases, when the CRP level was high, independent of the neutrophil count, almost all of them had high levels of the OCl− production/unit on the days of acute pharyngitis (the 35 y/o male), excess physical activity/influenza (the 54 y/o female) and cough variant asthma (the 35 y/o female)." (PMID 34267248, 2021). "The levels of inflammatory factors including C-reactive protein (CRP), tumor necrosis factor-alpha (TNF-α), and interleukin-6 (IL-6) in peripheral serum of children with asthma were significantly higher than those in the controls." (PMID 32158441, 2020).
asthma (continued). "Fraction of exhaled nitric oxide (FeNO), blood eosinophil (B-Eos) count, C-reactive protein (CRP), airway responsiveness to methacholine (PD20), and asthma-related quality of life (mAQLQ) were also measured." (PMID 30834110, 2019). "In this study we found that plasma levels of 8-isoprostane, CRP, total MMP-9, and 92-KDa MMP-9 activity were significantly increased in patients with asthma in acute exacerbation and decreased in remission but remained elevated compared with healthy controls." (PMID 24073339, 2013). "In addition, Disease subgroup analysis highlighted a prominent reduction in the levels of TNF-α (WMD: − 0.20; 95% CI − 0.34 to − 0.05; I2 = 97.10%) and CRP (WMD: − 0.29; 95% CI − 0.56 to − 0.02; I2 = 74.13%) in asthma patients." (PMID 41555409, 2026). "Notably, traditional biomarkers such as C-reactive protein (CRP) or eosinophil counts, while useful, often lack specificity to asthma and are influenced by a wide range of inflammatory conditions." (PMID 40546825, 2025). "There is a possibility that there may be a synergistic effect between asthma inflammation of the airway and systemic inflammation from OSA to increase CRP as a marker of disease severity." (PMID 40662069, 2025). "In asthma their CRP values normal to slightly raised, but not increase like those of their counterparts when have infection or inflammation." (PMID 40662069, 2025). "Increased levels of inflammatory markers have been demonstrated in patients with COPD and asthma, such as interleukin (IL)-6, tumor necrosis factor-alpha (TNF-α), IL-1β, C-reactive protein (CRP), as well as adipocytokines such as visfatin, apelin, adipolin, and FABP4." (PMID 37003999, 2023). "The clinical manifestations of acute asthma and bacterial RTI are similar, as are commonly used test values, like C-reactive protein (CRP) and white blood cell (WBC) count, making it harder for doctors to differentiate between viral and bacterial infections in asthma patients." (PMID 37627950, 2023). "Again, the clinical manifestations of acute asthma and bacterial RTI are similar, as are frequently used test values, like C-reactive protein (CRP) and white blood cell (WBC) count, making it harder for doctors to differentiate between viral and bacterial infections in asthma patients." (PMID 37627950, 2023). "This system includes clinical (peripheral nerve disorder, asthma, lung, and skin involvement), laboratory (RF positivity, MPO-ANCA positivity, IgE, and CRP elevation), and histological features (vasculitis detected by pathological examination), which have been awarded a point weight." (PMID 37215720, 2023). "Elevated levels of inflammation-related factors such as IL-6, C-reactive protein, and TNF-α are found in obese pregnant women, which may contribute to the development of wheezing and asthma in children." (PMID 37780583, 2022). "An interesting observation was that patients with MS in asthma had significantly higher CRP compared with those without MS." (PMID 34249177, 2021). "In a human cohort study, it was recently described that preschoolers suffering from rhinovirus-induces asthma and with reduced forced expiratory volume in 1 second (FEV1) and high serum levels of C-reactive protein (CRP) show increased level of PD-L1 mRNA in total blood cells." (PMID 34691038, 2021). "Similarly to asthma, OSAS promotes inflammatory responses by means of hypoxia, hypercapnia, and sleep fragmentation, resulting in a reversible increase in C-reactive protein (CRP)." (PMID 34277650, 2021). "Compared with the models with and without adjustment of BMI and CRP, the OR for asthma among the daily consumers of soft drink changed 10.0% (from 2.60 to 2.33)." (PMID 30871131, 2019). "In asthma patients, we also observed a negative correlation between A. muciniphila and circulating CRP levels." (PMID 31836714, 2019).
asthma (continued). "In particular, n-3 PUFA may be clinically relevant for an obese asthma population as our findings show lower ICS dose and CRP in this population with a higher O3I." (PMID 31892115, 2019). "This study is the first to demonstrate a correlation of AD disease severity with CRP levels in moderate-to-severe adult AD patients with decades of chronic disease activity, independent of co-existence of asthma." (PMID 29188018, 2017). "In the combined group of RA, severe asthma, ILD and RA-ILD patients, the level of cultured fibrocytes and CD45+ CD34+CD11b+ cells was significantly higher in the patients with normal C-reactive protein (CRP) (<10 mg/L) than in patients with elevated CRP (both p = 0.001)." (PMID 28720095, 2017). "The relationship between IL-8 responses and the asthma control category was also not influenced by plasma CRP levels, or residential proximity to the study area’s major roadway." (PMID 28424616, 2017). "Given the rural-urban pattern of IgG galactosylation levels, the pattern seen with CRP, total IgE, parasitic infections and children with and without asthma, we propose that reduced IgG1 galactosylation is a biomarker of immune activation." (PMID 27306703, 2016). "Although the association of high serum CRP and subsequent cardiovascular events in COPD has been shown, this association in asthma has not been documented and requires further studies." (PMID 26958331, 2016). "Clinical signs and symptoms of acute asthma and bacterial RTI overlap, as do commonly used laboratory parameters such as C-reactive protein (CRP) and white blood cell (WBC) count, making it difficult for physicians to distinguish viral from bacterial infections in asthma patients." (PMID 25189222, 2014). "Although an association between ARG1 polymorphisms and the level of CRP has not been reported, associations of ARG1 polymorphism with CVD and asthma have been reported." (PMID 24763700, 2014). "Children with asthma had higher serum CRP concentrations than those without, but the difference was not statistically significant." (PMID 17827864, 2007). "The main characteristic of asthma lies in eosinophilic inflammation yet this inflammatory process usually does not result in increased C-reactive protein (CRP) levels, but airway obstruction from OSA discourse may explain the CRP elevation." (PMID 40662069, 2025). "Furthermore, although it is not exclusive to asthma, CRP is a valuable additional biomarker to determine the global inflammatory response and adjust therapy in conditions where the general inflammation is involved." (PMID 40662069, 2025). "Furthermore, increased levels of C-reactive protein in asthma patients parallel the results observed in individuals with CKD, hinting at systemic inflammation as a potential mechanism contributing to CKD in asthma." (PMID 38343638, 2024). "CRP, the total gut bacterial load and gastrointestinal symptom score (GSRS) are positively related, which indicates that as the levels of peripheral blood inflammatory factors increase, the possibility of gut disorders and gastrointestinal inadaptability in children with asthma will increase." (PMID 38687096, 2024). "In addition, laboratory findings such as blood eosinophil count, C-reactive protein level, and bronchodilator response on spirometry or methacholine bronchoprovocation test for asthma severity were not measured." (PMID 36968830, 2023). "Comparing asthma group who did not have MS and asthma group with MS, there were significant differences between the 2 groups regarding waist circumference (P value= 0.0158), CRP (P value =0.025), DBP (P value =0.0157), triglycerides (P value = 0.0264), and fasting blood glucose (P value <0.0001)." (PMID 34249177, 2021). "Therefore, it seems that a decrease in plasma exosomal miR-130a expression in asthma patients regardless of the high levels of serum IgE and CRP can be effective in increasing the inflammatory process in inflammatory diseases such as asthma." (PMID 34001212, 2021).
asthma (continued). "Similarly, in a study of patients with relatively severe asthma, serum high-sensitively CRP did not correlate with wheeze, the National Asthma Education and Prevention Program (NAEPP) control score, FEV1, or fractional exhaled citric oxide (FeNO)." (PMID 26958331, 2016). "Children seldom have chronic diseases, but some planned controls for asthma and other diseases may explain some more consultations at daytime not taking a CRP." (PMID 26585447, 2015). "The present study aimed to investigate the suPAR, CRP and IL-6 levels in asthma (asthmatic non-pregnant, ANP; N = 38; female N = 27) and asthmatic pregnancy (AP; N = 15), compared to healthy non-pregnant controls (HNP; N = 29; female N = 19) and to healthy pregnant women (HP; N = 58)." (PMID 23565268, 2013). "However, the lack of specificity for blood parameters like ANC, BEC, and CRP are not specific to asthma, can be influenced by various systemic conditions, and do not provide direct information about the airway environment, leading to potential misinterpretation." (PMID 40872499, 2025). "Considering our findings, which demonstrate that a higher O3I in obese asthmatics is associated with lower CRP and maintenance ICS dose, n-3 PUFA supplementation may provide a unique nonpharmacological approach to treating asthma in this population and demands further research." (PMID 31892115, 2019). "The absence of spirometry data and key biomarkers, such as C-reactive protein (CRP) and interleukins, restricts a more comprehensive phenotypic and endotypic classification of asthma exacerbations." (PMID 40566622, 2025). "Doctors should interpret increased C-reactive protein results in people with OSA and asthma as indicators of OSA-related inflammation because this elevation does not stem from asthma conditions." (PMID 40662069, 2025). "There were statistically significant differences in the eosinophil counts, total IgE, and CRP, PCT, and LDH levels between the children with MPP with and without asthma." (PMID 36090550, 2022). "The liver acute phase proteins C-reactive protein (CRP), serum amyloid A (SAA) and fibrinogen were significantly elevated in the serum of obese non-asthma and obese asthma patients." (PMID 31836714, 2019). "CRP levels were higher in participants with both phenotypes of airflow obstruction (COPD p = 0.04, asthma p = 0.04) versus those without airflow obstruction." (PMID 27488495, 2016). "Participants with higher CVH tended to be younger, female, Non-Hispanic White, better educated, with a partner, more affluent, without CVD, no fumes at work, no second-hand smoke at home, no family history of asthma, with lower WBC, Hb, PLT, eosinophil, CRP, 2-NAP, 1-PYR, Pb, and Cd." (PMID 40319236, 2025). "ELSA-Brazil, Brazilian Longitudinal Study of Adult Health; USP, University of São Paulo; ICF, Informed Consent Form; CRP, C-Reactive Protein; mL, Milliliter; NOS, Non-Obstructed Smoker; ACO, Asthma-COPD overlap; FMUSP, Faculty of Medicine of the University of São Paulo." (PMID 40997602, 2025). "In addition, Laboratory results demonstrated that WBC, lymphocyte, neutrophil, plt, Hb, ALT, eosinophil, CRP, and ALKP were not significantly different between patients with and without post-hospitalization asthma-like." (PMID 35279094, 2022). "However, by looking closely at their clinical data, we found that the child with no IL-3 in the NPF had worse lung function and higher C-reactive protein (CRP), confirming a possible role of IL-3 in the amelioration of asthma." (PMID 35281014, 2022). "In contrast, workers with asthma had significantly higher SAA levels Monday morning (average = 57.0 mg/l) than Thursday noon (average = 44.7 mg/l) (p = 0.039 in paired t-test), this was not seen for CRP (average = 4.3 versus 3.1 mg/l p = 0.23)." (PMID 26792395, 2016).
asthma (continued). "With more evidence available, it might be possible to decide whether or not the application of chest findings, CRP testing and pulse oximetry can lead to improved patient outcomes related to COPD and/or asthma exacerbations." (PMID 25887285, 2015).